HES2 (hes family bHLH transcription factor 2)
Description:
Transcriptional repressor of genes that require a bHLH protein for their transcription.
Synonyms: bHLHb40
Tractability: No criterion of Open Targets' tractability assessment is met for any kind of drug.
Gene: Protein-coding gene on chromosome 1 (6,412,418 to 6,424,690, reverse strand). Ensembl gene ENSG00000069812.
Subcellular location: Nucleus
Gene Ontology:
Molecular function: sequence-specific double-stranded DNA binding; DNA-binding transcription factor activity, RNA polymerase II-specific; RNA polymerase II cis-regulatory region sequence-specific DNA binding; DNA binding; DNA-binding transcription repressor activity, RNA polymerase II-specific; double-stranded DNA binding; protein dimerization activity
Biological process: anterior/posterior pattern specification; negative regulation of transcription by RNA polymerase II; regulation of neurogenesis; negative regulation of DNA-templated transcription; regulation of DNA-templated transcription
Cellular component: chromatin; nucleus
Genetic constraint (gnomAD): Loss-of-function variants: 12 observed, 8.47 expected, observed/expected ratio (o/e) 1.42, 90% interval 0.89 to 1.91. That is too few expected variants to judge how well the gene tolerates losing a copy. Missense variants: 260 observed, 179.23 expected, observed/expected ratio (o/e) 1.45, 90% interval 1.31 to 1.61. Synonymous variants: 125 observed, 79.96 expected, observed/expected ratio (o/e) 1.56, 90% interval 1.35 to 1.81.
Homologues: Orthologues: chimpanzee HES2 (100% identical), macaque HES2 (91% identical), pig HES2 (80% identical), guinea pig HES2 (73% identical), dog HES2 (72% identical), mouse Hes2 (66% identical), rat Hes2 (66% identical), tropical clawed frog hes2 (46% identical), zebrafish hes2.2 (39% identical), zebrafish hes2.1 (36% identical), Drosophila melanogaster E(spl)mgamma-HLH (27% identical), Drosophila melanogaster E(spl)m3-HLH (26% identical), and 7 more. Paralogues in human: HES4 (42% identical), HES1 (39% identical), HES6 (31% identical), HES5 (29% identical), HEY1 (29% identical), HES7 (28% identical), HEYL (28% identical), HEY2 (27% identical), BHLHE41 (24% identical), HES3 (24% identical), BHLHE40 (23% identical), HELT (23% identical).
Diseases named in the same sentence as HES2 in open-access papers:
HES2 is named in the same sentence as 17 diseases in open-access papers, as found by Europe PMC text mining. Sharing a sentence is not in itself a finding about the gene and the disease. The quoted sentences say what the papers report.
Bardet-Biedl syndrome (1 paper, 2021). A ciliopathy with multisystem involvement. "For example, HES2, MAFB, RPS12, RPL12, RPS15, and AFF2 are all associated with cancer, whereas BBS12 is a gene related to Bardet-Biedl Syndrome, a multi-organ genetic disease that can involve hypoplasia of the uterus, ovaries, and fallopian tubes." (PMID 34215221, 2021).
endometriosis (1 paper, 2022). The growth of functional endometrial tissue in anatomic sites outside the uterine body. "Specifically, the expression of MSI-1, MSI-2, of the transcription factor HES-2 and the cell cycle regulator p21 are significantly reduced in patients with endometriosis according to the data." (PMID 35269992, 2022).
esophageal cancer (1 paper, 2023). A primary or metastatic malignant neoplasm involving the esophagus. "Esophageal cancer patients with high expression of FOXN1, GRHL3, and HES2, stomach cancer patients with high expression of ONECUT2, thyroid cancer patients with high expression of PAX8, and uterine cancer patients that expressed elevated levels of MECOM had decreased survival." (PMID 37627195, 2023).
leukemia (1 paper, 2013). A malignant (clonal) hematologic disorder, involving hematopoietic stem cells and characterized by the presence of primitive or atypical myeloid or lymphoid cells in the bone marrow and the blood. "Notch3, JAG1, Hes2, Hes4 and Hes5 were frequently hypermethylated in B leukemia cell lines and primary B-ALL, in contrast to T-ALL cell lines and patient samples." (PMID 23637910, 2013). "JAG1, Hes2 and Hes4 were commonly methylated in various leukemia cell lines and primary B-ALL and T-ALL but not in normal CD19+ B cells." (PMID 23637910, 2013). "Methylation verification revealed that Notch3, Hes5, Hes2, Hes4 and JAG1 genes were frequently hypermethylated in various leukemia cell lines but not in normal controls." (PMID 23637910, 2013). "Notch3, Hes5, Hes2, Hes4 and JAG1 genes were found frequently hypermethylated in various leukemia cell lines but not in normal controls." (PMID 23637910, 2013).
lung carcinoma (1 paper, 2025). "Expression levels of NOTCHs and their target genes (SNAI1, SNAI2, HES2, HEY2) are positively correlated with EMT scores in LUAD, indicating activation of the NOTCH pathway in mesenchymal lung cancer cells." (PMID 40189704, 2025).
tumor (5 papers, 2016 to 2024). "We also note the proapoptotic protein PMAIP1 (NOXA) that was downregulated in the drug-adapted tumors, and transcription factors NFIX, EGR1, and HES2 implicated in tumor promotion or suppression, which were differentially affected by LT everolimus and the drug combination." (PMID 39541354, 2024). "The expression of RSPO3, ALPP, VEGFC, ANXA8, HES2, GLP2R, and KRT14 in normal tissues was significantly higher than that in tumor tissues." (PMID 38240936, 2024). "In the PDTX model, administration of SR3029 obviously delayed tumor growth, concomitant with an increased protein level of AES and a decreased expression of Wnt target genes (Axin2, Fibronectin and LEF1), stemness marker genes (CD44 and LGR5) and Notch target genes (HES1 and HES2)." (PMID 33754069, 2021).
cancer (2 papers, 2015 to 2021). A tumor composed of atypical neoplastic, often pleomorphic cells that invade other tissues. "In contrast, transcripts encoding several canonical Notch signalling components, including DLL1, JAG1, NOTCH1 and HES2, were down-regulated in cancer cells." (PMID 25864518, 2015).
HES2 also shares sentences with these, for which no sentence is quoted: neuroblastoma (2 papers); breast carcinoma (1); genetic disease (1); melanoma (1); Obesity (1); stomach cancer (1); Stroke (1); thyroid cancer (1); type 2 diabetes (1); uterine cancer (1).